TSC22D3 (TSC22 domain family member 3)
Diseases named in the same sentence as TSC22D3 in open-access papers (continued):
Sharing a sentence is not in itself a finding about the gene and the disease.
tumor (35 papers, 2009 to 2025). "Mice with deficient TSC22D3 genes were shown to be infertile, and in humans, the gene is a known tumor suppressor which is often silenced in cancers via hypermethylation, though only hypomethylation was observed in our samples of peripheral leukocytes." (PMID 26913089, 2016). "In addition, TSC22D3 is thought to be involved in monitoring behaviors that disrupt anti-tumor immunity, and this behavior may be associated with altered psychological states of the body, such as stress." (PMID 40650680, 2025). "It is worth noting that TSC22D3 exhibits enhanced expression during T cell transformation and has clinical relevance in tumor staging." (PMID 41262126, 2025). "This receptor’s significance was emphasised by the reduced expression of the glucocorticoid-inducible factor Tsc22d3 (also known as glucocorticoid induced leucine zipper or GILZ) in Cyp11a1cKO tumour infiltrated immune cells, compared to control tumours." (PMID 40287432, 2025). "TSC22D3 plays a dual role in tumors: it not only exerts a tumor-promoting effect by influencing the immune system and tumor microenvironment but also inhibits tumor growth by inducing apoptosis or suppressing the proliferation of cancer cells." (PMID 37237254, 2023). "Yang and coauthors showed in a murine tumor model that SDS upregulated the expression of TSC22D3 in tumor-infiltrating DCs which was dependent on GR signaling." (PMID 33921690, 2021). "TSC22D3 promoted tumor cell proliferation by regulating AKT kinase." (PMID 37237254, 2023). "TSC22D3 could play an indispensable role in the tumor microenvironment by influencing all immune system cells that infiltrated the tumor microenvironment." (PMID 37237254, 2023). "Furthermore, TSC22D3 played a significant role in tumor progression by mediating the increase in cell quantity and activity of Treg cells through the TGF-β signaling pathway." (PMID 37237254, 2023). "It has been documented that efferocytosis is promoted in macrophages through the upregulation of Tsc22d3, suggesting that Tsc22d3 could play a crucial role in promoting tumor growth." (PMID 36732798, 2023). "TSC22D3 was overexpressed in NSCLC tumor B cells and PBL T cells." (PMID 35804895, 2022). "TSC22D3 is a glucocorticoid-inducible transcriptional regulator and also an immunosuppressive transcription factor, the activation of this gene will lead to immunosuppressive effect and the failure of the anti-tumor immunotherapy." (PMID 33996564, 2021). "Notably, TSC22D3 not only regulates cell growth, differentiation, and immune responses but may also partially inhibit anti-tumor immune responses." (PMID 40723340, 2025). "TSC22D3 may play an anti-inflammatory and immunosuppressive role in tumor development." (PMID 37237254, 2023). "However, recent studies suggested a wide spectrum of TSC22D3 functions in developmental regulation, reproduction, inflammation, and tumor suppression, and it may play a major role as a glucocorticoid-induced leucine zipper." (PMID 25520040, 2014). "UMAP clustering identified different triple-negative tumour cell clusters which were characterized by migration and GR signature and by NR3C1, and GR target SGK1 and TSC22D3 gene expression." (PMID 39905197, 2025). "TSC22D3, also known as glucocorticoid-induced leucine zipper (GILZ), can promote or suppress tumor growth, depending on the type of tumor and its microenvironment." (PMID 37237254, 2023). "TSC22D3 reduced the ability of DC to produce type I IFN and induce IFN-γ secretion in tumor-infiltrating T cells." (PMID 33921690, 2021). "This suggests that the role of TSC22D3 in IPTCC may not be limited to inflammation promotion, and its role in tumor immunity deserves further attention." (PMID 40650680, 2025).
cancer (23 papers, 2009 to 2025). A tumor composed of atypical neoplastic, often pleomorphic cells that invade other tissues. "Cancer-related stress induces GC excess, subverts anticancer therapy-induced immunosurveillance, and abolishes therapeutic control of tumors by Tsc22d3 upregulation and significant impairment of the antigen presentation pathway." (PMID 37114049, 2023). "In cancer patients, there is a close correlation among TSC22D3 expressions in circulating leukocytes." (PMID 35295188, 2022). "Importantly, TSC22D3 mediated immunosuppression and abolished the efficacy of immunogenic chemotherapy and suppressed cancer-preventive immunity strategies." (PMID 33921690, 2021). "Four gene markers, BARD1 (BRCA-associated RING domain 1), SOD2 (superoxide dismutase 2), S100A10, and TSC22D3 (TSC22 domain family member 3), were found to be the targets of several approved cancer drugs." (PMID 36430822, 2022). "We also detected significantly elevated expression of TSC22D3 in NK cells, CD8+ T cells, and monocytes of cancer-free TET2delA carriers." (PMID 30890702, 2019). "We found that both TSC22D3 and EEF2K exhibited biphasic dose- and time-dependent expression following cancer exosomes transfection." (PMID 30008265, 2018). "GC was found to promote TSC22D3 expression in dendritic cells, thereby blocking type-I IFN responses and IFNγ+ T-cell activation, which finally resulted in the compromise of therapy-induced anti-cancer immunosurveillance." (PMID 37210553, 2023). "A close correlation was found between plasma cortisol levels and TSC22D3 levels in leukocytes and negative moods in a group of cancer patients." (PMID 35295188, 2022). "Interestingly, cancer exosomes triggered a time-dependent bi-phasic effects on TSC22D3 and EEF2K gene expression whereby at 24 h incubation, they were dose-dependently upregulated but were then downregulated at 48 h incubation with cancer exosomes." (PMID 30008265, 2018). "Interestingly, TSC22D3 and EFF2K showed biphasic time-dependent effects in respond to cancer exosomes." (PMID 30008265, 2018). "In addition, a correlation between plasma CORT levels and TSC22D3 expression in PBMCs has been found in patients with cancer and negative mood." (PMID 33921690, 2021).
infection (9 papers, 2011 to 2023). The state of being infected such as from the introduction of a foreign agent such as serum, vaccine, antigenic substance or organism. "A transcriptome study of Atlantic salmon infected with Piscirickettsia salmonis showed a decrease in kidney expression level of TSC22D3 48 h post-infection." (PMID 25563603, 2015).
TSC22D3 also shares sentences with these, for which no sentence is quoted: Arthritis (12 papers); lupus (9); autoimmune disease (8); myeloma (7); acute kidney injury (5); endotoxemia (5); inflammatory bowel disease (5); multiple sclerosis (5); ovarian carcinoma (5); chronic rhinosinusitis (4); Crohn disease (4); thyroid cancer (4); acute respiratory distress syndrome (3); experimental autoimmune encephalomyelitis (3); injury (3); multiple myeloma (3); peritonitis (3); Sjögren’s syndrome (3); asthma (2); atherosclerosis (2); bacteremia (2); bacterial infection (2); benign tumors (2); breast carcinoma (2); cardiac hypertrophy (2); epithelial dysplasia (2); fibrosis (2); infectious disease (2); inflammation (2); male infertility (2).
A further 83 diseases each share a sentence with TSC22D3 in 2 papers or fewer.